CBFB (core-binding factor subunit beta)
Diseases named in the same sentence as CBFB in open-access papers (continued):
Sharing a sentence is not in itself a finding about the gene and the disease.
tumor (continued). "Having established that the CBFβ-depleted cells retain the ability to form localised tumours but have a restricted capacity to grow in osteoblast culture, we next tested their ability to establish bone metastases after injection into the circulation by intracardiac injection." (PMID 32005976, 2020). "Mutations with high VAFs indicated early appearance during tumorigenesis or tremendous contribution to later expansion of tumor cells, and the previous study demonstrated AKT1, CBFB, MAP2K4, ARID1A, FOXA1, and PIK3CA mutations have relatively high average VAFs in breast cancers." (PMID 33173047, 2020). "We then transfected CBFB_KO cells with plasmids expressing tumor-derived CBFB mutants." (PMID 31061501, 2019). "The CBFB gene plays a critical role in tumor cell growth and proliferation." (PMID 26870154, 2015). "Analyses of ∼1000 stage I–III adenocarcinomas, by immunohistochemistry, revealed that patients with tumours displaying high levels of CBFB and SMARCC1 proteins had a significantly better overall survival rate (P=0.0001 and P=0.0275, respectively) than patients with low levels." (PMID 19156145, 2009). "However, our understanding of the tumor suppressive function of CBFB remains incomplete." (PMID 33945523, 2021). "However, our understanding of the tumor suppressive functions of CBFB remains fragmented." (PMID 33945523, 2021). "It is worth noting that the tumor suppressive function of CBFB might be tumor subtype specific." (PMID 31061501, 2019). "Furthermore, expression of four proteins is associated with tumor progression/high risk AML: DOT1L, mTOR, VIM and ZNF521, whereas the expression of six proteins is associated with tumor suppression/low risk AML: AEBP2, CAST, CBFB, LSP1, MAP1S and probably PCBP1." (PMID 30634713, 2019). "As CBFβ-deficient cells are resistant to TNF and exhibit transcriptional and post-transcriptional alterations in the homoeostasis of copper and zinc ions, we next investigated whether exogenous supplementation of these ions would alter tumour cell sensitivity to TNF." (PMID 39261596, 2024). "In the tumor tissue of AML patients, the presence of RUNX1::RUNX1T1 and CBFB::MYH11 fusions positively affects the course of the disease." (PMID 38392574, 2024). "We identified three tumor suppressors: CTNNA1 (C772 and vicinal cysteine C767), GRIN2A (C320 and proximal C87), and CBFB (C25 and proximal C124)." (PMID 37085483, 2023). "Our findings showed that CBFβ depletion lowered the tumour TNF toxicity threshold, rather than completely abrogating TNF sensitivity." (PMID 39261596, 2024). "Patients with tumours showing strong staining had a significantly longer survival rate than patients with negative or weak scoring tumours (log-rank test; CBFB P=0.0001; SMARCC1 P=0.0275)." (PMID 19156145, 2009). "We then assessed the sensitivity of CBFβ -depleted cells (sgCbfb) to killing by CAR-T cells, compared to control tumour cells electroporated with a non-targeting sgRNA (sgNT)." (PMID 39261596, 2024). "E2F7 cooperated with CBFB-recruited RUNX1 in a non-canonical manner to transactivate ITGA2, ITGA5, and NTRK1, strengthening Akt signaling-induced tumor-promoting effect." (PMID 37028765, 2023).
adenocarcinoma (5 papers, 2009 to 2022). A common cancer characterized by the presence of malignant glandular cells. "In keeping with the association between low levels of CBFB protein and poor survival, we observed that cases with negative/weak CBFB protein levels were significantly enriched in metastasis cases compared with primary adenocarcinomas." (PMID 19156145, 2009). "In adenocarcinoma variations included somatic mutations in ELF3 (13%) and CBFB (8%) genes." (PMID 25220666, 2014).
infection (3 papers, 2014 to 2017). The state of being infected such as from the introduction of a foreign agent such as serum, vaccine, antigenic substance or organism. "To assess the impact of disruption of the CBFβ gene in the myeloid lineage we examined the outcome of intranasal (i.n.)infection of CBFβΔLysM mice and wild type (WT) control CBFβfl/fl littermates with a sublethal dose (0.1LD50) of the mouse adapted Influenza A strain A/PR/8 [H1N1]." (PMID 28085958, 2017). "However, CBFβΔLysM mice exhibited markedly reduced survival (> 85% mortality) following infection suggesting that expression of CBFβ in one or more cell types of the myeloid lineage was critical for recovery from IAV infection." (PMID 28085958, 2017). "Likewise, we also cannot formally exclude that alterations in the function of other LysM expressing cell types lacking CBFβ could also affect the susceptibility of T1AECs to infection, and therefore the outcome of infection in the CBFβΔLysM mice." (PMID 28085958, 2017). "As a control for RUNX3, CBFβ and IRF4 depletion experiments, EBNA2 ChIPs were performed in a similar manner, on the same batch of chromatin, after their infection with each shRNA-expressing lentivirus to show that the trend of reduced EBNA3 enrichment after knock-down was specific." (PMID 27903901, 2017).
blood cancers (2 papers, 2019 to 2022). "In FVPTC samples, LGALS3, an IA gene, is strongly associated with genes associated with blood cancers (RUNX1, BCL2L1, CBFB, and TNFRSF1A), suggesting a strong immune association in LGALS3 activity." (PMID 31443155, 2019).
degenerative disease (2 papers, 2021 to 2024). "Overall, the data presented in this paper sheds further light on how Wnt canonical signaling and Hippo/Yap signaling pathway are regulated by Cbfβ during OA pathogenesis, which may lead to novel therapies for the treatment of this degenerative disease." (PMID 38617544, 2024). "However, most of the current studies on Cbfβ have investigated osteogenesis and chondrogenesis, and whether the abnormal expression of Cbfβ has an impact on the degenerative disease of the articular cartilage remains unclear." (PMID 33573620, 2021). "However, the relationship between abnormal expression of Cbfβ and degenerative diseases like OA has not been clearly clarified up to now." (PMID 33573620, 2021).
hematological malignancies (1 paper, 2019). "In hematological malignancies, Circ-CBFB is overexpressed in CLL and is a sponge of miR-607, which promotes CLL cell proliferation but suppresses cell apoptosis via activating FZD3 and the following Wnt/β-catenin pathway." (PMID 31601173, 2019).
CBFB also shares sentences with these, for which no sentence is quoted: HIV-1 infection (5 papers); chronic myeloid leukemia (3); granulocytic sarcoma (3); lymphoid neoplasm (3); Myelodysplasia (3); acute lymphoblastic leukemia (2); kidney cancer (2); migraine (2); viral infection (2); acute erythroid leukemia (1); acute megakaryoblastic leukemia (1); anemia (1); bladder cancer (1); cervical adenocarcinoma (1); cervical cancer (1); developmental delay (1); endometrial cancer (1); essential thrombocythemia (1); glaucoma (1); graft versus host disease (1); hepatocellular carcinoma (1); Hyperglycemia (1); Hyperinsulinemia (1); lipodystrophy (1); lobular carcinomas (1); lung adenocarcinoma (1); lymphoma (1); lymphoproliferative disorders (1); mastocytosis (1); metastatic tumors (1).
A further 12 diseases each share a sentence with CBFB in 1 paper.